CXCR3 (C-X-C motif chemokine receptor 3)
Diseases named in the same sentence as CXCR3 in open-access papers (continued):
Sharing a sentence is not in itself a finding about the gene and the disease.
lupus nephritis (16 papers, 2013 to 2024). Glomerulonephritis in the context of systemic lupus erythematosus. "CXCR3 and its ligands have been widely implicated in the recruitment of T cells in target organs in varied inflammatory autoimmune disorders and immune-mediated kidney diseases among which lupus glomerulonephritis." (PMID 23520491, 2013). "Downregulation of CXCR3 significantly impairs the homing ability of hUC-MSCs to the kidneys of lupus nephritis mice." (PMID 39557841, 2024). "High CXCR3 expressions are found in the mesangium of kidney biopsies taken from active cases of lupus nephritis, IgA nephropathy, membranoproliferative glomerulonephritis, and rapidly progressive glomerulonephritis." (PMID 39768675, 2024). "The anti-ETAR antibody correlated with the anti-CXCR3 antibody in the groups of patients with lupus nephritis (p = 0.01) and IgA nephropathy (p = 0.001)." (PMID 39768675, 2024). "Conversely, overexpression of CXCR3 significantly augments the homing capacity of hUC-MSCs towards the diseased kidneys in lupus nephritis mice." (PMID 39557841, 2024). "For example, T-bet regulates CXCR3 expression and thus migration to sites of inflammation and into kidneys of mice with lupus nephritis." (PMID 29568300, 2018). "Segerer at al. demonstrated the infiltrate expressing CXCR3 in the tubulointerstitium in renal biopsies of patients with lupus nephritis with a correlation between the number of infiltrating CXCR3+ T cells and the degree of kidney dysfunction." (PMID 25866451, 2015). "In human patients with lupus nephritis, CXCR3 is similarly expressed on subpopulations of activated T cells and plasma cells as well as in a large proportion of CD4+ T cells that infiltrate the kidney." (PMID 24945254, 2014). "The results of the anti-CXCR3 antibody evaluation and correlation with clinical parameters of the patients suggest a negative influence of higher antibody levels with the course of IgA nephropathy and lupus nephritis." (PMID 39768675, 2024). "Moreover, there are data suggesting an inverse correlation between the glomerular CXCR3 expression in kidneys from patients with lupus nephritis and proteinuria in these group of patients." (PMID 39768675, 2024). "The positive correlation between anti-ETAR and anti-CXCR3 antibodies in the serum of lupus nephritis and IgA nephropathy patients may suggest systemic activation in these diseases." (PMID 39768675, 2024). "Anti-ETAR and anti-CXCR3 antibodies may be useful markers of IgA nephropathy and lupus nephritis prognosis." (PMID 39768675, 2024). "It was shown that CXCR3-deficient mice were partly protected from immune-mediated injury in both the nephrotoxic nephritis (NTN) model of crescentic glomerulonephritis and the MRL-Faslpr model of murine lupus nephritis." (PMID 33598825, 2021). "Due to the role of CXCR3 in recruitment and infiltration of Th1 and Th17 and induction of renal injury, it is possible that the studied probiotics, through reduction of CXCR3, inhibit migration of DCs to inflammation site and reduce injury in lupus nephritis." (PMID 35317107, 2021). "Th1 and Th17 responses are both decreased after CXCR3 deletion in a lupus nephritis model." (PMID 29868034, 2018). "Indeed, CXCR3 bearing CD4+T cells infiltrating the inflamed kidneys have been detected in patients with active lupus nephritis." (PMID 24069401, 2013). "Indeed, kidney infiltration by CXCR3-expressing CD4+ T cells has also been detected in patients with active lupus nephritis, suggesting that the pathogenesis of the abdominal type is closely related to Tfh1 cells; refractory cases in particular merit further exploration." (PMID 29236760, 2017). "CXCR3 mediates kidney disease in murine lupus nephritis, and reduction of the transcription factor FLI1 results in amelioration of kidney disease in MRL/lpr mice with concomitant reduction in CXCR3+ T cells and CXCL9/10 expression." (PMID 29568300, 2018).
lupus nephritis (continued). "Our data, in combination with accessible data, suggest a negative influence of anti-CXCR3 antibodies on the course of lupus nephritis." (PMID 39768675, 2024). "Although CXCR3 escape has not yet been convincingly demonstrated in human T cells, CD4+ T cells from patients with SLE exhibit female-biased overexpression of CXCR3, and CXCR3+ CD4+ T cells are enriched in the urine and inflamed kidneys of patients with active lupus nephritis." (PMID 35510951, 2022). "Furthermore, Cxcr3 was upregulated in monocytes and monocyte-like cells from IMQ-treated mice by RNA-seq analysis, which was in accordance with the recently reported importance of the IP-10/CXCR3 axis in human lupus nephritis." (PMID 35371102, 2022).
glioblastoma (15 papers, 2016 to 2025). The most malignant astrocytic tumor (WHO grade IV). "In this study, we demonstrated that CXCR3 expression correlates with glioblastoma (GBM) grading, with CXCR3-A isoform being associated with poorer patient prognosis compared to CXCR3-B." (PMID 40185710, 2025). "Lipoprotein receptor-related protein-1 (LRP1) enhances the internalization of CXCR3 by regulating clathrin and reduces the number of CXCR3 on the cell membrane and the invasiveness of glioblastoma, and it is often downregulated in the invasive region." (PMID 39429695, 2024). "Tregs are reported to be recruited to the TME of glioblastoma by specific cytokines such as CXCR3 and CCR5, which can be secreted by glioblastoma cells and innate immune cells within the brain." (PMID 39061427, 2024). "CXCR3 is widely expressed by activated T cells and was highly enriched on glioblastoma-infiltrating T-cell subsets." (PMID 35464424, 2022). "Like CD4+ glioblastoma T cells, CXCR3 was expressed moderately by all CD8+ T-cell subsets, and there was a significantly greater proportion of CXCR3+CD8+ Tem cells in glioblastoma biopsies compared to paired blood samples." (PMID 35464424, 2022). "A study investigating the role of CXCR3 signalling in glioblastoma observed that CXCR3-KO mice had a reduced survival compared to WT mice." (PMID 35464424, 2022). "Subsequent analysis showed that CTLA-4 was tightly associated with CXCR3, CXCR6, CXCL12, and T cell immunoreceptor with Ig and ITIM domains (TIGIT) in patients with glioblastoma." (PMID 31911758, 2020). "The CXCR3 pathway in the CNS plays a role in diseases, including glioblastoma, traumatic optic neuropathy (TON), neuropathic pain, and CNS degenerative diseases such as Alzheimer's disease (AD), multiple sclerosis (MS), prion diseases (PrD), and bipolar disorder (BD)." (PMID 39429695, 2024). "Together, our flow cytometry analysis demonstrates that CCR5 and CXCR6 are expressed by large proportions of all glioblastoma-infiltrating CD4+ T-cell subsets, whereas CCR2 and CXCR3 enrichment was only observed in glioblastoma-infiltrating CD4+ Tcm and Tregs, and Tem and Tregs respectively." (PMID 35464424, 2022). "Identifying the function of CXCR3 will better instruct the use of immunotherapies to treat glioblastoma via augmenting CXCR3 expression on CAR T cells infused via the CSF to improve entry to the brain, or improve T cell-DC interactions to enhance anti-tumour responses when paired with ICI therapy." (PMID 35464424, 2022). "We then investigated whether CXCR3 signaling in glial cells was able to regulate cytokine production negatively using an in vitro experiment with a glioblastoma cell line, U87MG, which expresses CXCR3." (PMID 27068264, 2016). "Therefore, these discrepancies highlight the need for future studies using immunocompetent mouse glioblastoma models as it is unclear whether CXCR3 mediates infiltration or positioning of T cells within glioblastoma." (PMID 35464424, 2022). "Evidence suggests CXCR3 works as an oncogene by inducing glioblastoma multiforme (GBM) cell invasion and migration, and high CXCR3 expression correlates with poor survival in primary GBM patients." (PMID 35794867, 2022). "It has been well documented that blocking NF-kB decreases CXCR3 expression and CXCL10 in an autocrine feedback loop, thereby reducing glioblastoma cell proliferation." (PMID 38104126, 2023). "Overall, CCR5 and CXCR4 show the most prominent expression on CD8+ T-cell subsets in glioblastoma tissues, with CCR2, CXCR3 and CXCR6 displaying subset-specific glioblastoma enrichment in Tcm, Tem, and Tcm and Temra populations respectively." (PMID 35464424, 2022). "They confirmed that the receptors CCR2, CCR5, CXCR3, CXCR4, CXCR6, CD49a, and CD49d were more abundant in the glioblastoma-infiltrated T cell population compared with peripheral blood." (PMID 36479091, 2022).
glioblastoma (continued). "Having identified that CCR2+, CCR5+, CXCR3+, CXCR4+, and CXCR6+ T-cell subsets were enriched in glioblastoma, we subsequently validated the expression of complementary chemokines in dissociated glioblastoma biopsies and patient-derived glioblastoma cell-lines." (PMID 35464424, 2022). "CXCR3+ cells were abundant in all CD4+ T-cell subsets, however enrichment was only statistically significant in CD4+ Tem and Tregs in glioblastoma biopsies compared to paired blood samples." (PMID 35464424, 2022). "Treatment of glioblastoma cells with poly(I:C) led to enhanced attraction of CTL and, to a lesser extent, of Th cells via CXCR3 and CCR5 signaling by inducing a proinflammatory secretome in vitro." (PMID 34203660, 2021). "The CXCR3 and LRP1 interaction was also evidenced in vivo in U87-CXCR3-A CAM tumors and in patient-derived glioblastoma cells." (PMID 29146996, 2017). "Representative histograms for CD4+ T-cell subsets illustrate the typical chemokine receptor expression patterns observed, and demonstrate that staining for CCR2, CCR5, CXCR3 and CXCR6 was robust in glioblastoma-infiltrating T-cell populations compared to matched blood naïve CD4+ T cells." (PMID 35464424, 2022). "Within glioblastoma-infiltrating T cells, a large proportion of cells were positive for CXCR4 and the proportion of cells positive for chemokine receptors CCR4, CCR5, CCR6, CCR7, CXCR3, and CXCR6 ranged between 5-25%." (PMID 35464424, 2022). "Subsequently, chemokine receptors and integrins were validated at the protein level to reveal enrichment of receptors CCR2, CCR5, CXCR3, CXCR4, CXCR6, CD49a, and CD49d in glioblastoma-infiltrating T-cell populations relative to T cells in matched patient peripheral blood." (PMID 35464424, 2022). "In our study, we screened primary glioblastoma data from the TCGA and CGGA databases and found that only CXCR3, CXCR4, and CXCR5 mRNA expression differed significantly between the two databases, suggesting that these members may be more closely linked in the onset and progression of GBM." (PMID 37626511, 2023). "However, glioblastoma-infiltrating T-cell numbers were not significantly different between groups, suggesting that CXCR3 did not mediate infiltration of T cells in this model." (PMID 35464424, 2022). "used high‐throughput tissue microarrays to detect CXCR3 and CXCL10 immuno‐expression in glioblastoma multiforme (GBM) and diffuse astrocytoma (DA) tissues." (PMID 35702353, 2022).
cerebral malaria (14 papers, 2009 to 2024). A sequestration of Plasmodium falciparum in the brain, which can cause coma and/or seizures. "However, a study in the murine model revealed an upregulated CXCR3 expression in NK cell and T-cell and its association with lymphocyte trafficking during cerebral malaria and mice deficient in CXCR3 was found efficiently protected from cerebral malaria." (PMID 31614626, 2019). "However, in the case of Plasmodium berghei ANKA, CXCR3 is pathogenic because it allows entry of proinflammatory cells into the CNS, resulting in cerebral malaria." (PMID 24130498, 2013). "The genetic deletion of CXCL-10 (CXCL-10-/-) or of its receptor CXCR3 (CXCR3-/-) in experimental cerebral malaria (ECM) studies involving Plasmodium berghei ANKA infections attenuates ECM pathogenesis and mortality." (PMID 31844087, 2019). "AT1R−/− OT-I cells also exhibit lower expression of the integrin LFA-1 and the chemokine receptors CCR5 and CXCR3, known to play a key role in the development of cerebral malaria." (PMID 28261571, 2017). "Studies using CXCR3 knockout mice have demonstrated that this damage is mediated by CD8+ T cells which are recruited by CXCR3, and CXCR3- mice fail to develop cerebral malaria." (PMID 24472559, 2014). "As CXCR3 is a crucial chemokine receptor in the migration of T cells to the brain during cerebral malaria, we studied its expression in spleen and brain lymphocytes." (PMID 24498110, 2014). "CXCL10 functions as a chemokine and deletion of its receptor, CXCR3, is protective in experimental cerebral malaria." (PMID 23874969, 2013). "Using a rodent model of cerebral malaria, we have previously found that during infection, inflammatory leukocytes are recruited to the brain via the CXCR3 trafficking pathway." (PMID 19343215, 2009). "Using a rodent model of cerebral malaria, we have previously found that the majority of T lymphocytes in intravascular infiltrates of cerebral malaria-affected mice express the chemokine receptor CXCR3." (PMID 19343215, 2009). "Overall, these findings demonstrate that modulation of PTP activity could possibly be utilized in the treatment of cerebral malaria and other CXCR3-mediated diseases." (PMID 28710387, 2017). "While CXCR3 can be pathogenic by recruiting effector cells to otherwise healthy tissue, as in IBD or cerebral malaria, we show here that CXCR3-expressing T cells play an essential protective role in host defense by enabling defense against pathogenic organisms." (PMID 24130498, 2013). "In the subsequent erythrocytic stage of infection, NK cells also induce protection through Th1-type cytokines but, in addition, may also promote development of cerebral malaria via CXCR3-induction on CD8+ T cells resulting in migration of these cells to the brain." (PMID 24498110, 2014). "However, future analysis is necessary to confirm or investigate this hypothesis, mainly by evaluating the production levels of CCL2, CCL4, CXCL4, CXCL8, CXCL10, and the receptors CXCR3 and CCR2, correlated with susceptibility to cerebral malaria and lung inflammation." (PMID 38256880, 2023). "Finally, NK cells have been shown to promote development of murine cerebral malaria, as NK cell depletion results in inhibition of T cell recruitment to the brain of Plasmodium berghei-infected animals, which correlates with the down-regulation of the chemokine receptor CXCR3." (PMID 24498110, 2014). "We first clarified the roles of Heme/HO-1, CXCL10/CXCR3 and STAT3 in CM pathogenesis utilizing a well established experimental cerebral malaria mouse (ECM, P. berghei ANKA) model." (PMID 22479586, 2012). "Recent studies in our laboratory and others have revealed a hitherto unknown correlation between chemokine CXCL10/CXCR3, Heme/HO-1 and STAT3 and cerebral malaria severity and mortality." (PMID 22479586, 2012). "CXCR3 expression was increased on spleen and brain CD4+ T cells in cerebral malaria mice compared to non-infected mice." (PMID 24498110, 2014).
osteosarcoma (14 papers, 2008 to 2025). A usually aggressive malignant bone-forming mesenchymal neoplasm, predominantly affecting adolescents and young adults. "For instance, decreased CXCR3 expression predicted poor prognosis of osteosarcoma and CXCR3 expression was positively associated with immune infiltration of CD8+ T cells, M1 macrophages, plasma cells, and activated NK cells." (PMID 36030223, 2022). "The association of low CXCR3 expression with the prognosis were further explored in various clinicopathological features, such as age, gender, and metastasis status of osteosarcoma patients." (PMID 31696204, 2019). "We further explored insight into the biological pathways modulated via CXCR3 and investigated whether CXCR3 was associated with immune infiltration in osteosarcoma." (PMID 31696204, 2019). "Therefore, the stratified analysis showed that low CXCR3 expression was associated with a worse EFS in female osteosarcoma patients, patients aged less than 15.1 years, and patients without metastasis." (PMID 31696204, 2019). "CXCR3 was associated with immune infiltration in osteosarcoma." (PMID 31696204, 2019). "Additionally, we further explored the prognostic role of CXCR3 expression in various clinicopathological variables of osteosarcoma and found that low CXCR3 expression was still significantly associated with worse OS in females, patients aged less than 15.1 years, or patients without metastasis." (PMID 31696204, 2019). "Inhibiting CXCR3 in pre-clinical models resulted in inhibition of lung metastases in several tumour types (breast, colon, osteosarcoma)." (PMID 39146303, 2024). "We found that IHC staining exhibits that all the protein expression of CXCL9, CXCL11/CXCR3 axis was significantly elevated in osteosarcoma tissues compared with adjacent normal tissues (bone, marrow, soft tissue and cartilage)." (PMID 32820615, 2020). "Osteosarcoma with low CXCR3 expression showed an unfavorable prognosis than that with high CXCR3 expression (OS: P=0.00082; EFS: P=0.0022)." (PMID 31696204, 2019). "Then, the objective of the present study was to extensively evaluate the correlation between CXCR3 and the clinicopathological features and the prognosis in osteosarcoma." (PMID 31696204, 2019). "More clinical and experimental studies should be conducted to further validate the role of CXCR3 in osteosarcoma." (PMID 31696204, 2019). "In conclusion, the present study demonstrated that CXCR3 in osteosarcoma was correlated with poor prognosis and immune cell infiltration." (PMID 31696204, 2019). "In this work, our study was the first to demonstrate that low CXCR3 expression was related to histologic response and worse prognosis of osteosarcoma, which is consistent with the previous studies." (PMID 31696204, 2019). "In osteosarcoma, studies suggest that CXCR3 and its ligands induce metastasis to the lungs and later stimulate growth and expansion of the metastases." (PMID 24259307, 2013). "In the osteosarcoma samples tested, CXCR3 was found expressed on scattered mononuclear infiltrating cells." (PMID 18215331, 2008). "In addition, CXCR3 antagonism by AMG487 inhibited lung metastasis in a mouse osteosarcoma model and metastatic colon cancer model." (PMID 36479091, 2022). "In our study, we found CXCR3 acts like protective factor in osteosarcoma." (PMID 32820615, 2020). "CXCR3 and its ligands have the same role in promoting lung metastasis of osteosarcoma." (PMID 32974202, 2020). "Among them, we mainly focused on the role of CXCR3 in osteosarcoma in our study." (PMID 31696204, 2019). "This suggested that CXCR3 played a crucial role in immune infiltration in osteosarcoma." (PMID 31696204, 2019). "Thus, CXCR3 may serve as a useful prognostic biomarker and could serve as a novel therapeutic target of osteosarcoma." (PMID 31696204, 2019). "Thus, we further analyzed whether CXCR3 expression was related to immune infiltration in 80 osteosarcomas, including 22 immune cell types." (PMID 31696204, 2019).